FOXO1 (forkhead box O1)
Diseases named in the same sentence as FOXO1 in open-access papers (continued):
Sharing a sentence is not in itself a finding about the gene and the disease.
prostate carcinoma (continued). "Forkhead box transcription factor-1 (FOXO1) is a tumor suppressor that is downregulated in human prostate cancer, which acts as a repression target of EZH2 and an essential mediator of EZH2 inhibition-induced cell death." (PMID 32264916, 2020). "In the present study, we identify FOXO1 as a direct downstream target gene of EZH2 in prostate cancer and other cancer types." (PMID 31410199, 2019). "Immunohistochemistry was employed to assess the correlation between EZH2 and FOXO1 protein expression in prostate cancer patient specimens." (PMID 31410199, 2019). "EZH2 protein level inversely correlated with FOXO1 protein expression in prostate cancer patient specimens." (PMID 31410199, 2019). "While several mechanisms have been proposed for the downregulation of FOXO1, our data uncover a novel mechanism whereby increased level of EZH2 in prostate cancer results in repression of FOXO1 expression." (PMID 31410199, 2019). "We further explored the clinical relevance of EZH2 and FOXO1 expression in an independent cohort of prostate cancer patient specimens (n = 42) using IHC." (PMID 31410199, 2019). "Along this way, the miR-182 dependent reduction of FoxO1 levels renders prostate cancer cells more prone to proliferation and invasion." (PMID 30646603, 2019). "Most importantly, we identified FOXO1 as a key mediator of EZH2 inhibition-induced death of prostate cancer cells." (PMID 31410199, 2019). "As we known, FOXO1 played an important role in many cellular processes, including cell growth, proliferation, and apoptosis, in prostate cancer cells; and also, FOXO1 was a key downstream target of PI3K/AKT pathway." (PMID 29533017, 2018). "On the other hand, high expression of MAOA in human tissues correlates with poor prognostic in prostate cancer patients and increased tumor metastasis in xenograft mouse model of prostate cancer via HIF1-α/VEGF-A/FOXO1/TWIST1 signaling pathway." (PMID 29334991, 2018). "Conversely, it will be important to verify if other known targets of miR-182, like FOXO1 in prostate cancer, are also deregulated in GBM." (PMID 29383111, 2017). "The results of this study are consistent with previous reports demonstrating that FOXO1 inhibits Twist1 mRNA expression in prostate cancer cells." (PMID 27924058, 2017). "For example, FOXO1 antagonizes AR activity and its downregulation contributes to increased metastatic activity of prostate cancer cells." (PMID 28055971, 2017). "It has been revealed that miR-96 plays an anti-apoptotic function in bladder and prostate cancer through suppression of FOXO1 expression by targeting its 3′UTR." (PMID 25888950, 2015). "The action of paclitaxel and bicalutamide is partly supported by the findings that taxanes are known to inhibit the androgen-independent activation of AR by the action of FOXO1 in prostate cancer." (PMID 25781993, 2015). "In this regard, methylseleninic acid (MSA), a chemical compound previously shown to reactivate FOXO1 in prostate cancer, was tested in Ewing sarcoma cells." (PMID 26258070, 2015). "The loss of PTEN in prostate cancer cells leads to activation of AKT and phosphorylation and retention of FOXO1 in the cytoplasm." (PMID 26204939, 2015). "For example, in prostate cancer, FOXO1 is found transcriptionally downregulated and the induction of its expression in prostate cancer cells inhibits cell proliferation and survival." (PMID 26258070, 2015). "It was reported in43, 44 that FOXO1 acts downstream on PTEN to induce the apoptosis of prostate cancer cells." (PMID 26603105, 2015). "It was reported in42 that FHL2 inhibits FOXO1 activity in prostate cancer cells by promoting the deacetylation of FOXO1 through SIRT1 on DU145." (PMID 26603105, 2015). "In this study, they found that miR-370 expression level was upregulated in prostate cancer cell lines as compared to normal prostate epithelial cells and miR-370 directly targeted the FOXO1 3′UTR." (PMID 25628647, 2014).
prostate carcinoma (continued). "FOXO1 activation inhibits tumor cell survival by inducing apoptosis in prostate cancer and glioma cells through upregulating proapoptotic factors." (PMID 24864265, 2014). "A study in prostate cancer cells suggested that overexpression of FOXO1 resulted in apoptosis via increased expression of TRAIL (TNF-Related Apoptosis-Inducing Ligand)." (PMID 24962166, 2014). "miR-96 is over-expressed in prostate cancer cells and was found to promote prostate cancer cell proliferation by suppressing FOXO1 and SLC39A1." (PMID 25333253, 2014). "Suppression of FoxO1 levels in prostate cancer PC3 cells by siRNA knockdown inhibited cellular autophagy, both under basal conditions and that induced by rapamycin or serum and glucose deprivation." (PMID 25546383, 2014). "It is also known that mir-223 regulates cell proliferation through targeting and downregulating FOXO1, and upregulation of miR-370 promotes proliferation of prostate cancer cells by suppressing the expression FOXO1." (PMID 25472505, 2014). "One of the predicted targets, FOXO1 was chosen for further validation due to its known tumorsuppressive function in prostate cancer." (PMID 24260486, 2013). "RT-qPCR and immunohistochemistry of 69 prostate cancer specimens revealed a downregulation of FOXO1 and an inverse correlation of miR-96 and FOXO1 protein expression." (PMID 24260486, 2013). "Beside the technical pitfalls, it is probable that miR-96 targets several other pro-apoptotic molecules beside FOXO1 in prostate cancer, which results in a predominant inhibition of apoptosis." (PMID 24260486, 2013). "In conclusion, we show that miR-96 can regulate apoptosis in prostate cancer, by inhibiting the FOXO1 transcription factor." (PMID 24260486, 2013). "Transfection of a miR-370 inhibitor restored the luciferase activity of the pGL3-FOXO1-3′UTR reporter plasmid in PC3 and DU145 prostate cancer cells, and upregulated FOXO1 protein expression." (PMID 23029264, 2012). "FOXO1 is involved in prostate cancer cell migration and invasion as a critical negative regulator of Runx2." (PMID 23029264, 2012). "Conversely, expression of FOXO1 restores the tumor suppressor function of FOXO1 and reduces prostate cancer cell growth and survival." (PMID 23029264, 2012). "Phosphorylation of FOXO1 attenuates the tumor suppressor function of FOXO1, and induces prostate cancer cell growth and survival." (PMID 23029264, 2012). "In conclusion, these results suggest that miR-370-induced prostate cancer cell proliferation is directly mediated by suppression of FOXO1." (PMID 23029264, 2012). "Taken together, our results suggest that miR-370 plays an important role in the proliferation of human prostate cancer cells, by directly suppressing the tumor suppressor FOXO1." (PMID 23029264, 2012). "MiR-370 upregulated the cell-cycle regulator cyclin D1 by directly targeting the FOXO1 3′-UTR, demonstrating that FOXO1 is regulated by miR-370 in prostate cancer cells." (PMID 23029264, 2012). "A recent study demonstrated that hemizygous and homozygous deletions within the FOXO1 gene locus are present in approximately 30% of prostate cancer cell lines, xenografts and a cohort of human prostate cancers." (PMID 23029264, 2012). "It is the first for us to uncover the new relationship of regulation of FOXO1 and microRNA in prostate cancer." (PMID 23029264, 2012). "To confirm the effect of miR-370 overexpression in prostate cancer cells, we quantified the expression of FOXO1 in prostate cancer cells." (PMID 23029264, 2012). "In contrast, ectopic expression of FOXO1 induces apoptosis in certain cancer cells, including prostate cancer cells." (PMID 23029264, 2012). "FOXO1 has been shown to restrain the migration and invasion of prostate cancer cells." (PMID 38778150, 2024). "This indicates that the involvement of FOXO1 in MDM2 expression may be cell type–dependent and that transcription factors other than FOXO1 may regulate MDM2 expression in prostate cancer cells." (PMID 38519029, 2024).
prostate carcinoma (continued). "TP63 and FOXO1 inhibit prostate cancer lineage plasticity and RORC promotes it." (PMID 38778150, 2024). "A tumor-suppressive role for FOXO1 has been shown in prostate cancer cell lines." (PMID 38519029, 2024). "SGK2 knockdown inhibited the metastatic capacity of prostate cancer cells in vivo and in vitro, while SGK2 overexpression inhibited ferroptosis and facilitated prostate cancer metastasis by phosphorylating the Thr-24 and Ser-319 sites of forkhead box O1 (FOXO1)." (PMID 36720852, 2023). "Furthermore, analysis of tumor tissue using the prostate cancer-specific pathway array revealed the alteration of several genes involved in PCa growth and progression including Forkhead O1 (FOXO1)." (PMID 38201438, 2023). "The anti-proliferative role of FOXO1 has been reported in case of cervical and prostate cancer, moreover, the enforced expression of FOXO1 in endometrioid endometrial cancer cells and SiHa cells blocked the cell proliferation and decreased the tumorigenic activity." (PMID 35309123, 2022). "Nevertheless, in variety of other cancer miR-27a, miR-96, and miR-182 act as oncomiRs to suppress FOXO1, including renal cell cancer, bladder cancer, Prostate cancer, colorectal cancer, thyroid carcinoma, ovarian cancer, liver cancer, gastric cancer, adenocarcinoma, and cervical cancer." (PMID 36539739, 2022). "Researchers found that the second-ranked HAS-miR-96b was found to regulate apoptosis of prostate cancer cells by inhibiting the FoxO1 transcription factor, indicating that the HGCNELM subsequently validates the predictive ability of HGCNELMDA in new diseases without any known linked miRNAs." (PMID 35879658, 2022). "We fully studied the influence that the FOXO1 expression brought to prostate cancer patients." (PMID 34552661, 2021). "miR-96-5p promotes prostate cancer cells proliferation by targeting tumor suppressor gene FOXO1." (PMID 33331954, 2021). "In addition, another study shows that four-and-a-half LIM 2 (FHL2) interacts with FOXO1 to facilitate SIRT1-mediated deacetylation to reduce FOXO1 activity in prostate cancer." (PMID 32372224, 2020). "In prostate cancer, FoxO1 was regulated by miR-96, promoting cancer progression." (PMID 32766159, 2020). "Together, these findings suggest FOXO1/3 act as tumor suppressors during prostate cancer." (PMID 32630372, 2020). "Furthermore, FOXO1 also cooperates with FOXA1 to function as pioneer factors to facilitate AR binding in prostate cancer." (PMID 32372224, 2020). "Oncomining of previously reported RNA-seq data generated from prostate cancer clinical specimens 46 showed that EZH2 expression negatively correlated with FOXO1 at the mRNA level in a cohort containing both primary and metastasis prostate cancers (r = - 0.55; P = 1e-8)." (PMID 31410199, 2019). "In addition, EZH2 expression negatively correlates with FOXO1 protein level in both cultured cancer cell lines and prostate cancer patient specimens." (PMID 31410199, 2019). "In support of this notion, mouse genetic studies show that while deletion of FOXO1 alone is insufficient to induce tumorigenesis in the mouse prostate, FOXO1 loss cooperates with TMPRSS2-ERG fusion, the most frequent genetic alteration in human prostate cancers to promote tumorigenesis." (PMID 31410199, 2019). "MiR-370 has been shown to be a FOXO1 gene regulator in prostatic cancer cells." (PMID 31920988, 2019).
prostate carcinoma (continued). "Activation of FOXOs (such as FoxO1 in prostate cancer cells) triggers cell cycle arrest and induces cell apoptosis via increasing the levels of Fas‐L (Fas ligand), TRAIL (tumor necrosis factor‐related apoptosis‐inducing ligand), and Bim in various types of cells." (PMID 29533017, 2018). "The group also investigated the miRNA-mRNA pathway using prostate cancer cell lines and demonstrated that miR-96 could bind FOXO1 mRNA, which is a tumor suppressor, resulting in a reduction of FOXO1 protein thus, increasing cell growth and proliferation." (PMID 30200254, 2018). "Interestingly, expression of PTEN and the level of FOXO1 in the nucleus inversely correlate with RUNX2 expression in prostate cancer specimens from patients with lymph nodes or bone metastasis." (PMID 26204939, 2015). "Increased FOXO1 activation may limit the metastasis of the prostate cancer cells to other organs by inhibiting the migration and invasion through inhibition of Runt-domain containing protein Runx2 transcriptional activity." (PMID 24864265, 2014). "Recent reports have indicated that deacetylation of FOXO-1 by SIRT1 could enhance VEGF-C transcription in the nuclei of prostate cancer cells and facilitate the growth of endothelial cells in mice." (PMID 25922660, 2014). "In the next step, we assessed, whether FOXO1 has an opposing role to miR-96 in prostate cancer cells and whether the effect might be rescued by cotransfection with miR-96." (PMID 24260486, 2013). "To further support the hypothesis that miR-96 controls FOXO1 in prostate cancer and thereby protects cells from apoptosis, we transfected LNCaP and DU145 cells with a full length FOXO1 cDNA." (PMID 24260486, 2013). "FOXO1 has been characterized as a key tumor suppressor in prostate cancer." (PMID 23029264, 2012). "Growing evidence suggests that activation of FOXO1 induces apoptosis in prostate cancer cells." (PMID 23029264, 2012). "We observed that FOXO1 is downregulated in prostate cancer cells; confirming that overexpression of miR-370 downregulates the miR-370 target gene FOXO1 in prostate cancer cells." (PMID 23029264, 2012). "Furthermore, the growth rate of both PC3 and DU145 prostate cancer cells was inhibited to a significantly greater extent by co-transfection of miR-370 and FOXO1 than co-transfection of FOXO1-3′-UTR and miR-370." (PMID 23029264, 2012). "Thus, the function of FOXO1 is frequently abolished via various mechanisms in human prostate cancer, further confirming the role of FOXO1 as a tumor suppressor." (PMID 23029264, 2012). "This study suggests that upregulation of miR-370 may provide an alternative mechanism for the reduced expression of the FOXO1 tumor suppressor protein in prostate cancer cells." (PMID 23029264, 2012). "Additionally, in prostate cancer cells, FOXO1 has been shown to promote the upregulation of VEGFC." (PMID 38899748, 2024). "Notably, the FOXO1 gene is frequently lost due to genomic deletion or transcriptional downregulation in human cancers such as prostate cancer 22, implying that it may function as a tumor suppressor during prostate tumorigenesis." (PMID 31410199, 2019). "Our analysis revealed that several maize miRNAs potentially target key regulators of prostate-cancer signaling, including PTEN, IGF1R, AR, FOXO1, GSK3B, and BCL2." (PMID 41440174, 2025). "Module 2 includes TGFBR3, FOXO1, RSPO3, PLAG1, and CYLD, which have been shown to play a role in mediating or inhibiting prostate cancer progression." (PMID 39347576, 2024).
prostate carcinoma (continued). "The transcriptional activities of NKX2-5, RUNX1, TRPS1, FOXO1, and TP63 are negatively correlated with LEGs, suggesting these suppress prostate cancer lineage plasticity through the RTK/RAS pathway." (PMID 38778150, 2024). "The process of the RTK/RAS pathway driving prostate cancer lineage plasticity is a complex interplay involving multiple TFs, with TP63, FOXO1, and RORC potentially playing more crucial roles due to their relatively high activity levels." (PMID 38778150, 2024). "Particularly, TFs TP63 and FOXO1 suppress and RORC drives prostate cancer lineage plasticity through the RTK/RAS pathway." (PMID 38778150, 2024). "The CNVs and TFs, such as TP63, FOXO1, and RORC, promote the RTK/RAS pathway-driven prostate cancer lineage plasticity by upregulating the LEGs." (PMID 38778150, 2024). "FOXA1, a gene family that includes FOXO1, promotes cell proliferation and inhibits cell motility and EMT in prostate cancer cells." (PMID 38571514, 2024). "NKX2-5, RUNX1, TRPS1, FOXO1, and TP63 play a inhibitory roles in the development of prostate cancer." (PMID 38778150, 2024). "Gene deletion of the tumor suppressors FOXO1 and FOXO3 is frequently observed in late-stage prostate cancer." (PMID 36768610, 2023). "This drives the EHMT-mediated silencing of tumor suppressor genes such as forkhead Box O1 (FOXO1), GATA binding protein 5 (GATA5), and N-myc downstream regulated 1 (NDDRG1) in prostate cancer." (PMID 35740522, 2022). "It has been demonstrated that ERβ suppresses tumor growth and induces apoptosis by augmenting the transcription of the tumor-suppressor genes FOXO1 and FOXO3 in prostate cancer." (PMID 35574319, 2022). "The following mechanism is likely: EZH2 inhibits FOXO1 expression and may serve as a target of EZH2 inhibitors, which can be used to overcome EZH2 inhibitor resistance in PTEN mutant cancers or to treat PTEN-deficient prostate cancer in combination with taxane." (PMID 34149432, 2021). "RUNX2, in turn, plays an important role in prostate cancer cells, and its expression was shown to be regulated via a PTEN/AKT/forkhead box protein O1 (FOXO1) axis." (PMID 34064589, 2021). "Increasing evidence has suggested that FOXO1 is a key downstream effector of PTEN and in an array of human cancers which include prostate cancer, gastric cancer, and lung cancer, and it acts as the tumor suppressor." (PMID 34552661, 2021). "It is believed that the FOXO1 gene is a new inhibitory target of EZH2 and FOXO1 is a key mediator of EZH2 inhibition and induction of prostate cancer cell death." (PMID 34149432, 2021). "Common genetic alterations within the three prostate cancer datasets analyzed were observed in PTEN, DEPTOR, SGK3, FOXO1/3, MAP3K7, RRAGD, SESN1, PIK3CA, PIK3C2B, and PDPK1." (PMID 32630372, 2020). "The FOXO1-derived peptide inhibitor overcomes drug resistance against the PI3K and paclitaxel in prostate cancer cells." (PMID 31591479, 2020). "miR-96 can mediate cell proliferation and cell growth through FOXO1 inhibition in prostate cancer and miR-183 can regulate PTEN, which is a known tumor suppressor in prostate cancer." (PMID 30200254, 2018). "We further experimentally validated that miR-486-5p directly suppresses the expression of PTEN, FOXO1 and SMAD2, and then contributes to prostate cancers, which makes it subject to complex regulation by miRNAs." (PMID 29069829, 2017). "KLF5 is generally repressed in prostate cancer samples and cell lines and acts as a tumor suppressor via an interaction with ERβ, CBP, or FOXO1." (PMID 26474386, 2015). "FOXO1 interacts with RUNX2 in vitro and in prostate cancer cells, and inhibits RUNX2 transcriptional activity on the OP, IL8, VEGF and MMP13 genes." (PMID 26204939, 2015). "Upregulation of tumor necrosis factor related apoptosis inducing ligand (TRAIL) by increased levels of FOXO1 or FOXO3 in cancer cells, such as prostate carcinoma cells, leads to apoptosis." (PMID 32309538, 2013).